INS (insulin)
Diseases named in the same sentence as INS in open-access papers (continued):
Sharing a sentence is not in itself a finding about the gene and the disease.
parasitic infection (10 papers, 2014 to 2025). "A study conducted in children’s hospital in Addis Ababa revealed that the most common precipitating factors were infection (52%), omission of insulin (16%) and parasitic infection (12%)." (PMID 35381004, 2022). "The level of insulin signaling in the muscles feeds back on the systemic control of metabolism, which in turn affects the ability of the immune defense to cope with a parasite infection." (PMID 29146985, 2017). "Similar to the metabolic switch from oxidative phosphorylation to aerobic glycolysis in cancer cells, during bacterial, mycobacterial, or parasitic infections, insulin signaling components (FOXO, PI3K, and Akt) contribute to metabolic wasting hastening the death of the host." (PMID 26791145, 2016). "Future studies would need to investigate the generalizability of the role of insulin-activated T cells in primary lymphedemas, which present earlier in life with a genetic etiology, or other secondary lymphedemas such as in relation to the parasitic disease filariasis." (PMID 40821816, 2025). "Importantly, DEX increased plasma glucose levels in Adx mice at their peak of parasitemia, 8 to 10 days p.i., without significantly affecting insulin levels." (PMID 30375380, 2018). "Thus, parasitic infection results in a shift from insulin-dependent to non-insulin dependent transporters and magnifies the contribution of paracellular glucose absorption." (PMID 24465430, 2014).
pituitary tumor (10 papers, 2011 to 2025). A benign or malignant neoplasm affecting the pituitary gland. "Patients with pituitary tumours had significantly higher fasting insulin levels (p = 0.004), and in the case of HbA1c, the result was close to the threshold of significance (p = 0.074)." (PMID 41234225, 2025). "After the resection of the pituitary tumor, our patient was advised to stop insulin treatment, which was not only effective in regulating blood glucose levels, but also lowered triglyceride levels significantly (68.07 vs. 2.88 mmol/L)." (PMID 34039339, 2021). "The effect of insulin physiological doses on the levels of triiodothyronine (T3)- stimulated GH mRNA in rat pituitary tumor cells had been studied earlier." (PMID 33586392, 2021). "Insulin (7 nmol/ L) selectively suppressed T3- stimulated GH mRNA levels in pituitary tumor cells by 58%." (PMID 33586392, 2021). "In addition, in our study, we noted higher fasting insulin levels and triglycerides levels and lower HDL cholesterol levels in the group of patients with pituitary tumours." (PMID 41234225, 2025). "Endocrinological data show that in men with nonfunctioning pituitary tumors, the cortisol peak values in the GHRP-2 loading test correlate well with the insulin tolerance test." (PMID 40308384, 2025).
respiratory distress syndrome (10 papers, 2012 to 2025). "Excess insulin has been demonstrated to delay surfactant production, thus elevating the risk of respiratory distress syndrome (RDS)." (PMID 41228398, 2025). "The excess of insulin in the fetal circulation can delay pulmonary maturation associated with the low production of surfactant leading to the respiratory distress syndrome or hyaline membrane disease." (PMID 22964143, 2012). "It was found that patients with GDM treated with insulin had a higher likelihood of LGA newborns, respiratory distress syndrome, neonatal jaundice, or admission to the neonatal intensive care unit." (PMID 38256447, 2024).
sensitivity (10 papers, 2010 to 2025). "The primary causes of insulin hypersensitivity reactions (IHRs) include protamine sulfate, preservatives such as cresol and phenol, and the insulin molecule itself." (PMID 40869188, 2025). "Restriction of bedtime (4 hours per day per 6 days vs.12 hours per day per 6 days) has been associated with cardiovascular risk factors including impaired insulin sensitivity." (PMID 20148113, 2010). "Mechanistically, glucose, insulin, and insulin-like growth factors (IGFs) can promote cancer cell growth and progression, especially in insulin-sensitive cancers, which are where the indirect effects of metformin are based." (PMID 37344841, 2023).
acute respiratory distress syndrome (9 papers, 2019 to 2025). Progressive and life-threatening pulmonary distress in the absence of an underlying pulmonary condition, usually following major trauma or surgery. "Here, we report the case of an extreme and transitory insulin requirement episode in a type 2 diabetic patient presenting an acute respiratory distress syndrome caused by SARS-CoV-2." (PMID 33066762, 2020). "Here, we report the case of an extreme and transitory high-dose insulin requirement episode in a diabetic patient presenting an acute respiratory distress syndrome (ARDS) caused by SARS-CoV-2." (PMID 33066762, 2020).
Alström syndrome (9 papers, 2008 to 2025). "Here we investigated the role of Alms1 disruption in AT expansion and insulin responsiveness in a murine model for Alström Syndrome." (PMID 25299671, 2014). "Even when matched for pubertal stage and body composition, individuals with Alström syndrome are much more severely insulin resistant than controls." (PMID 22043170, 2011). "A defective function of ALMS1 in the target tissues of insulin action, as well as in central nervous system is probably responsible for the clinical features of Alström Syndrome." (PMID 20108502, 2008).
androgenic alopecia (9 papers, 2015 to 2024). "We present a 57-year-old man with androgenic alopecia who was treated with tirzepatide monotherapy and had significant improvement in hair density within 6 months, alongside improvement in insulin resistance and weight loss." (PMID 39135763, 2024). "Insulin may contribute to androgenic alopecia through vasoconstriction and nutrient deficiency, along with enhancement of the effects of testosterone." (PMID 39135763, 2024). "In contrast, other studies established clear connections between insulin resistance and androgenic alopecia." (PMID 39135763, 2024). "In line with previous studies, men with early-onset androgenic alopecia were characterized by increased androgen levels and impaired insulin sensitivity." (PMID 34106452, 2021). "Parameters of MeTS like insulin resistance are present in patients with early onset androgenic alopecia, hidradenitis suppurativa acne and rosacea." (PMID 29483947, 2018). "These various mechanisms demonstrate how insulin resistance, leading to increased insulin levels, may contribute to miniaturization of hair follicles, worsening androgenic alopecia." (PMID 39135763, 2024). "A recent case report described significant hair regrowth in a patient with androgenic alopecia treated with tirzepatide for insulin resistance, suggesting that improved insulin sensitivity might promote hair growth." (PMID 39845205, 2024). "In this study, 81 female-to-male transsexuals treated with testosterone esters had male-pattern baldness without any cardiovascular disease risk factors such as increased blood pressure, levels of lipid, and insulin." (PMID 26617635, 2015).
benign prostatic hyperplasia (9 papers, 1975 to 2026). A non-cancerous nodular enlargement of the prostate gland. "Elevated insulin levels during IR contribute to prostate enlargement and can lead to the condition of Benign Prostatic Hyperplasia (BPH)." (PMID 41987603, 2026). "Excess adipose tissue may affect inflammation, lipid metabolism, insulin resistance, and adipokine levels with a plausible role in prostate enlargement and LUTS pathophysiology." (PMID 27336586, 2016). "The properties of human benign prostatic hyperplasia (BPH) and rat prostate were compared after culture in the absence of insulin and testosterone." (PMID 50856, 1975).
co-infection (9 papers, 2010 to 2025). "Effects of co-infection on blood glucose, serum insulin as well as liver and gastrocnemius muscle glycogen concentration were determined using one-way analysis of variance (ANOVA), followed by Bonferroni post hoc test." (PMID 35923890, 2022). "Co-infection also affected expression of gigas, which produces the Tsc2 protein in the Drosophila insulin signaling pathway." (PMID 24245482, 2013). "However, the effect of Pb + Tz co-infection on insulin, liver and muscle glycogen concentration remains obscure." (PMID 35923890, 2022). "However, there is still a paucity of information on how this phenomenon influences glucose homeostasis, insulin and glycogen levels during co-infection." (PMID 35923890, 2022). "Animal models are ideal to elucidate effects of co-infection on disease outcomes and hence, blood glucose, insulin and glycogen profiles were assessed in Sprague-Dawley rats co-infected with P. berghei ANKA (Pb) and Trichinella zimbabwensis (Tz), a tissue-dwelling nematode." (PMID 35923890, 2022). "However, there is continued paucity of information on how the co-infection influence the blood glucose and insulin profiles in the infected host." (PMID 35923890, 2022). "What is most striking is that co-infection of CIP with p25, resulted in a similar rescue of insulin secretion to control levels (lane p25+CIP)." (PMID 24039692, 2013). "Moreover, the correlation between serum insulin and serum FASN was maintained irrespective of HCV co-infection or altered ALT values in HIV-infected patients." (PMID 20707918, 2010).
complication (9 papers, 2008 to 2025). Any disease or disorder that occurs during the course of, or because of, another disease, treatment, or procedure. "Insulin is essential for cardiac contractility, growth, and metabolism, thus impaired insulin signaling plays a key role in diabetic cardiovascular complications." (PMID 36818396, 2023).
corneal ulcer (9 papers, 2016 to 2025). Area of epithelial tissue loss from corneal surface; associated with inflammatory cells in the cornea and anterior chamber. "In the current study we used a single intrastromal injection of 0.1 mL of the dye with a 27-gauge insulin needle at the center of the cornea at the middle of the stroma depending on the sense of the surgeon with decreased risk of corneal ulceration or recurrent erosion." (PMID 27195146, 2016). "Although the systemic steroid dose had been increased from 20 mg to 40 mg one month prior to topical insulin initiation, the corneal ulcer remained refractory at the time." (PMID 40621257, 2025). "Concerned about the threat of imminent perforation of the corneal ulcer in the OD, topical insulin drops (4 i.d.; 1 U/mL) were initiated, along with a CL and topical fluoroquinolone." (PMID 40621257, 2025). "Topical insulin has demonstrated effectiveness in promoting healing of persistent epithelial defects, including neurotrophic corneal ulcers." (PMID 40733109, 2025). "While the role of topical insulin in promoting epithelial cell growth and migration in corneal ulcers is well established, its effectiveness in controlling oGVHD is not well established in the literature." (PMID 40621257, 2025). "Following the treatment of the perforation, the patient’s oGVHD-related DES and subsequent corneal ulcer were successfully managed with topical insulin." (PMID 40621257, 2025). "Materials and Methods: This retrospective case–control study included 32 patients with facial nerve palsy and lagophthalmos who developed an exposed corneal ulcer, of whom 20 received topical insulin and 12 received lipid-based artificial tears." (PMID 41303828, 2025). "All studies displayed promising results with topical insulin use, with almost all patients achieving complete re-epithelialization of their corneal ulcers/epithelial defects with restoration of corneal sensation." (PMID 38989397, 2024). "The literature search yielded 33 eyes (32 patients) across seven studies evaluating the use of topical insulin for the management of corneal ulcers or epithelial defects secondary to NK." (PMID 38989397, 2024). "In the years since the use of topical insulin to treat corneal ulcers was first described, several authors (including this research group) have published case series showing that compounded insulin eye drops are an effective and safe means of treating PED." (PMID 38794241, 2024). "Following the initial study that highlighted the potential of insulin to improve corneal ulcer healing, additional research in this area stalled." (PMID 38276493, 2023). "In this case, topical insulin was utilized to treat a corneal ulcer associated with oGVHD and to control DES, which had not been achieved with previous treatments." (PMID 40621257, 2025). "Furthermore, this case adds to the scarce literature on the use of topical insulin for treating refractory corneal ulcers and DES in oGVHD, demonstrating its potential as a novel therapeutic approach in these challenging cases." (PMID 40621257, 2025). "Topical insulin has recently emerged as a potential treatment for neurotrophic corneal ulcers." (PMID 40621257, 2025). "Multiple in vitro and preclinical studies have demonstrated that insulin promotes proliferation, migration, and desquamation of corneal epithelial cells (CECs), while modulating inflammatory processes essential for corneal ulcer healing and maintaining corneal transparency." (PMID 41303828, 2025). "This early research highlighted improvement in corneal ulcer healing after systemic administration of insulin, setting a precedent for further studies to explore its potential applications in ophthalmology, and posing both diagnostic and therapeutic dilemmas for ophthalmologists." (PMID 38276493, 2023).
corneal ulcer (continued). "ILGF-1 could be useful likely as insulin eye drops, which have shown great effectiveness in closure of corneal ulcers, with the added advantages of retaining water to prevent desiccation, reducing the number of applications, and maintaining optical transparency." (PMID 38239894, 2024). "Importantly, topical insulin administration provides local benefits without systemic risk of hypoglycemia, making it a promising safe and effective therapeutic strategy for patients with chronic or neurotrophic corneal ulcers." (PMID 41303828, 2025). "Within three days of treatment, the OD corneal ulcer was completely re-epithelialized, and the patient continued on topical insulin with progressive tapering to twice per day without additional medication." (PMID 40621257, 2025). "A retrospective analysis of six patients with neurotrophic corneal ulcers who had failed to respond to standard medical and surgical treatments demonstrated that topical insulin may be a safe and effective therapy." (PMID 41303828, 2025).
deafness (9 papers, 2010 to 2024). An inherited or acquired condition characterized by the complete loss of the ability to hear from one or both ears. "Specifically, young women with characteristics such as short stature, slender physique, low BMI, sensorineural deafness, or family history, together with negative results on tests for pancreatic autoantibodies and low insulin secretion should undergo early genetic sequencing." (PMID 39432645, 2024).
diabetic encephalopathy (9 papers, 2015 to 2024). A brain disease that is characterized by functional impairment of cognition, cerebral signal conduction, neurotransmission and synaptic plasticity, and underlying structural pathology associated with diabetes. "Aβ is always tangled with insulin signaling pathway in diabetic encephalopathy and stagnates insulin receptor in the cytosol." (PMID 31551793, 2019). "Metabolic abnormalities, impaired insulin signaling, neuronal apoptosis, oxidative stress, and inflammation are all involved in the development of diabetic encephalopathy (DEP)." (PMID 30823412, 2019). "Insulin treatment inhibited ROS, AGEs, and RAGE and contributed to the expansion of diabetic encephalopathy." (PMID 38639646, 2024). "Moreover, as insulin is reported to modulate Aβ degradation and is involved in neuronal function and memory formation, insulin resistance in various brain regions, including the cerebellar cortex and hippocampus, may lead to diabetic encephalopathy." (PMID 36372924, 2023). "It is concluded that insulin exerts direct anabolic actions in neuron-like cells by activation of its cognate receptor and proves that IGF-1R plays an important role of in the pathogenesis of diabetic encephalopathy." (PMID 26089889, 2015). "However, because insulin can cross-activate the insulin-like growth factor type 1 receptor (IGF-1R), which also functions in most of tissues, such as muscle and bone, it has been difficult to establish the direct (IGF-1-independent) actions of insulin in the pathogenesis of diabetic encephalopathy." (PMID 26089889, 2015).
electrolyte disorders (9 papers, 2007 to 2025). "The mainstays of DKA management include careful fluid resuscitation, timely intravenous insulin administration, restoration of shifting electrolyte disorders and addressing underlying precipitating factors." (PMID 37568965, 2023). "Possible side effects are hypotension, hypovolaemia, electrolyte disorders, insulin resistance and reduced insulin secretion and increased risk of infection." (PMID 20370902, 2010). "Possible side effects are hypotension, hypovolaemia, electrolyte disorders, insulin resistance, reduced insulin secretion, and increased risk of infection." (PMID 17298665, 2007).
female infertility (9 papers, 2012 to 2025). Diminished or absent ability of a female to achieve conception. "Of particular interest are hyperglycemic challenges and the consequent changes in liver-secretory protein(s) and insulin sensitivity affecting the maturation of ovarian follicles, potentially leading to female infertility." (PMID 37108615, 2023). "The FGF21-Tg mice share other phenotypic similarities with long-lived dwarf mice including small size, reduced circulating insulin and IGF-1 concentrations, increased circulating adiponectin levels and female infertility." (PMID 23066506, 2012).
goiter (9 papers, 2017 to 2025). Enlargement of the thyroid gland usually caused by lack of iodine in the diet, hyperthyroidism, or thyroid nodules. "A long-term insulin stimulation in thyroid follicular cells leads to cell proliferation and thus goiter." (PMID 34454459, 2021). "Metformin has a neutral effect on goiter, whereas insulin therapy possibly exerts a protective role against the formation of nodular goiter." (PMID 29214182, 2017).
hyperphosphatemia (9 papers, 2020 to 2025). Abnormally high level of phosphate in the blood. "Some studies have demonstrated the harmful effect of Pi on insulin secretion in chronic renal patients associated with hyperphosphataemia and “Klotho”-deficient mice (kl/kl)." (PMID 34360534, 2021). "Because hyperphosphatemia reportedly promotes oxidative stress in cultured insulin-secreting and endothelial cells, we wondered whether enhanced ROS production also contributes to high Pi-mediated suppression of skeletal muscle cell differentiation." (PMID 33136552, 2020).
hyperproinsulinemia (9 papers, 2004 to 2025). "In obese men, 10-CLA induces hyperproinsulinemia that is related to impaired insulin sensitivity (hyperinsulinaemic-euglycaemic clamp), independently of changes in insulin concentrations." (PMID 19761624, 2009). "It would follow that delayed MSG production could result in the increased release of ISGs and hyperproinsulinemia, and thus a failure of the β-cell to respond to glucose with the secretion of insulin." (PMID 34436456, 2021).
Hypoglycemic coma (9 papers, 2006 to 2025). Coma induced by low blood sugar. "This case was a pregnant diabetic woman in hypoglycemic coma after misuse of insulin, which was reverted after a short period of time." (PMID 21810265, 2011). "For instance, diabetic children on conventional insulin therapy sustain about 20 hypoglycemic comas and convulsions per 100 patient years." (PMID 18320053, 2008). "The use of therapeutic insulin and other external hypoglycemic agents have also been employed to control the glucose level in blood, yet they are not capable enough to mimic the natural activity of endogenous insulin and may result in a hypoglycemic coma." (PMID 30046616, 2018).